ING5 (inhibitor of growth family member 5)
Diseases named in the same sentence as ING5 in open-access papers (continued):
Sharing a sentence is not in itself a finding about the gene and the disease.
lung carcinoma (continued). "Furthermore, it has been reported that ING5 may inhibit cancer aggressiveness via prevention of the epithelial-mesenchymal transition in breast cancer and lung cancer." (PMID 28490335, 2017). "ING5 overexpression might suppress the proliferation, migration and invasion, induce apoptosis, autophagy, and differentiation, and mediate chemotherapeutic resistance of lung cancer cells." (PMID 27409347, 2016). "Therefore, it has to be possible to employ ING5 as a target of gene therapy for lung cancer if its chemoresistance could be overcome." (PMID 27409347, 2016). "Consistent with another report, cytoplasmic ING5 was negatively associated with lymphatic invasion of lung cancer, which might be attributable to no wide and careful application of D2-40 immunostaining in the pathological diagnosis." (PMID 27409347, 2016). "In ING5-overexpressed A549 cells, we detected an increased expression of E-cadherin which is a hallmark of EMT and often lost in metastatic tumors, while the expression of SNAIL, Slug and N-cadherin was downregulated, suggesting that ING5 inhibit lung cancer cell invasion by suppressing EMT." (PMID 25938545, 2015). "Furthermore, we have found, for the first time, that ING5 could inhibit migration and invasion of lung cancer cells by both in vitro and in vivo study, suggesting a role for ING5 in preventing lung cancer metastasis." (PMID 25938545, 2015). "Although a high ING5 expression was observed in gastric, breast, and colorectal cancers, ING5 was found to be expressed in osteosarcoma, prostate cancer, ovarian cancer, HCC, lung cancer, esophageal cancer, and thyroid cancer at a low level." (PMID 36425530, 2022). "Meanwhile, ING5 knockdown promoted migration and invasion through up-regulating EGFR/PI3K/Akt signaling pathway in lung cancer cells." (PMID 32308564, 2020). "In addition, studies concerning lung cancer showed that ING5 knockdown-induced EMT was abolished upon treatment of cells with WNT/β-catenin inhibitor, suggesting that ING5 inhibits EMT via WNT/β-catenin signalling." (PMID 34685579, 2021). "Notably, there is very limited data available on the effect of ING3 in lung cancer, whereas the function of ING1, ING2, ING4, and ING5 has been investigated in lung cancer in more detail." (PMID 31390718, 2019). "Our results indicate an indispensible role of ING5 in preventing EMT and metastasis in lung cancer." (PMID 28903339, 2017). "We hypothesized that there could be a correlation between ING5 tumor suppressive function and PI3K/Akt and STAT3 signaling in lung cancer." (PMID 28903339, 2017). "In other words, ING5 up-regulated the apoptotic level of lung cancer cells, but had no ability to induce their apoptotic level against chemodrugs." (PMID 27409347, 2016). "Univariate analysis using Kaplan-Meier method indicated that either nuclear or cytoplasmic ING5 expression was no related with the survival rate of the patients with lung cancer (p > 0.05)." (PMID 27409347, 2016). "In conclusion, our results demonstrate that ING5 could inhibit EMT and aggressiveness of lung cancer cells by downregulating EMT-inducing genes." (PMID 25938545, 2015). "ING5 expression was not related to age or tumor size of lung cancer (p > 0.05)." (PMID 27409347, 2016). "ING5 overexpression up-regulated the expression of pro-apoptotic proteins AIF and cytochrome c, and down-regulated the expression of anti-apoptotic proteins Bcl-2, XIAP and survivin, accounting for its apoptosis-induced role in lung cancer cells by mitochondrial pathway." (PMID 27409347, 2016). "ING5 expression was detected in cytoplasm and nuclei in both lung cancer and non-cancerous tissues." (PMID 25938545, 2015). "In order to see whether cancer and normal cell lines have the same expression pattern like tissues, we extracted cytoplasmic, nuclear and total proteins from lung cancer A549 and H1299 cells and normal human bronchial epithelial cell line HBE cells and detected ING5 protein level by western blot." (PMID 25938545, 2015).
breast carcinoma (15 papers, 2015 to 2025). "The higher expression of nuclear ING5 was inversely linked to worse clinicopathological behaviors of breast cancer by in vivo and vitro reversing aggressive phenotypes." (PMID 29137236, 2017). "For example, a genome-wide functional screen by Mendes-Pereira identified ING5 as one of the set of genes whose silencing caused sensitivity to tamoxifen in breast cancer therapy regimens." (PMID 28490335, 2017). "In another study the silencing of ING5 caused sensitivity to tamoxifen in MCF7 breast cancer cells, indicating that repression of ING5 expression is associated with tumor cell progression." (PMID 25860957, 2015). "Here, we found that ING5 significantly suppressed proliferation, glucose metabolism, migration, invasion and tumor growth, and induced the apoptosis and autophagy, but caused the chemoresistance in breast cancer cells, in line with the previous reports." (PMID 29137236, 2017). "To determine the molecular mechanism underlying ING5 downregulation in breast cancer, we used computational bioinformatics to predict those miRNAs that could target ING5 and identified miR-24." (PMID 28490335, 2017). "To investigate the biological consequences of the downregulation of ING5 expression caused by miR-24 in breast cancer, we analyzed the effects of miR-24 on cell proliferation, invasion and apoptosis after the overexpression or the knockdown of miR-24 in MCF-7 cells." (PMID 28490335, 2017). "For instance, ING5 expression has been found to be elevated in breast cancer samples compared with normal tissues." (PMID 35804879, 2022). "CAF (cancer-associated fibroblast)-derived exosomal miR-196a confers cisplatin resistance in HNSCC cells by targeting ING5, and miR-193a-3p induces the chemoresistance of breast cancer cells by targeting ING5, in line with the effects of ING5 silencing." (PMID 36425530, 2022). "The low nuclear expression of ING5 and its nucleocytoplasmic translocation were involved in the tumorigenesis of gastric cancer, breast cancer, HNSCC, and colorectal cancer." (PMID 36425530, 2022). "Other studies in animal models of breast cancer, glioma, and ovarian cancer have shown that the over-expression of ING5 significantly reduces tumor weight and enhances apoptosis and autophagy." (PMID 35804879, 2022). "Some researchers have confirmed that the expression of ING5 in paracancerous tissues of breast cancer is significantly higher than that in cancerous tissues." (PMID 33469513, 2020). "Quantitative real-time PCR and western blot were used to examine the expression levels of ING5 in breast cancer tissues." (PMID 28490335, 2017). "In the present study, we observed the effects of ectopic ING5 overexpression on the aggressive phenotypes of breast cancer cells, and analyzed the relevant molecular mechanisms." (PMID 29137236, 2017). "In breast cancer, ING5 mRNA expression was positively with relapse- and distant metastasis-free survival rates." (PMID 29262575, 2017). "Then, we used TCGA’s, Curtis’s, Gluck’s, and Finak’s datasets to perform bioinformatics analysis, and found that ING5 mRNA expression was higher in breast cancer than normal tissue (p < 0.05)." (PMID 29137236, 2017). "We also investigated the potential function of ING5 in breast tumorigenesis and found that ING5 suppressed the proliferation and invasion of breast cancer cells and promoted their apoptosis." (PMID 28490335, 2017). "Here, we for the first time investigated the molecular mechanisms about inhibitory effects of ING5 on EMT of breast cancer cells." (PMID 29137236, 2017). "Adipophilin (ADFP) is a ubiquitous component of lipid droplets, and its overexpression enhanced the fat accumulation in ING5-overexpressing breast cancer cells." (PMID 29137236, 2017).
breast carcinoma (continued). "The ING5 protein levels were significantly lower in breast cancer tissues than in the paired normal tissues." (PMID 28490335, 2017). "In breast cancer, ING5 has been found to be downregulated and efficiently inhibited the epithelial-mesenchymal transition of cancer cells." (PMID 28490335, 2017). "Cytoplasmic ING5 expression was positively correlated with tumor size and ER expression of breast cancers (p < 0.05), and lower in triple-negative breast cancer (TNBC) than non-TNBC (p < 0.05)." (PMID 29137236, 2017). "Spearman correlation analysis showed that there was a trend of inverse correlation between the miR-24 levels and ING5 protein levels in paired breast cancer samples." (PMID 28490335, 2017). "Stronger expression of cytoplasmic ING5 was detectable in the elder patients with breast cancer than younger ones (p < 0.05)." (PMID 29137236, 2017). "Overexpression of ING5 significantly inhibited the proliferation and invasion of breast cancer cells, but stimulated apoptosis, while knockdown of ING5 had the opposite effects on these cellular functions." (PMID 28490335, 2017). "The up-regulated expression and nucleocytoplasmic translocation of ING5 protein existed in breast cancer." (PMID 29137236, 2017). "Taken together, these results portray a novel regulatory pathway employing miR-24 and ING5 to fine-tune the balance of breast cancer cells." (PMID 28490335, 2017). "The disparity between the levels of ING5 protein and ING5 mRNA expression in breast cancer tissues strongly implies that a post-transcriptional mechanism is involved in ING5 regulation in breast cancer." (PMID 28490335, 2017). "In the present study, we performed a systematic analysis of ING5 expression in breast cancer and identified ING5 as a direct target of miR-24." (PMID 28490335, 2017). "In TNBC, nuclear ING5 expression was negatively related to distant metastasis of breast cancers (p < 0.05)." (PMID 29137236, 2017). "This study also showed for the first time that miR-24 accomplishes its oncogenic effects by negatively regulating ING5 expression in breast cancer." (PMID 28490335, 2017). "ING5 expression was examined in breast cancers and their precancerous diseases, and compared with the clinicopathological parameters of breast cancers to explore the roles of ING5 expression." (PMID 29137236, 2017). "miR193 binds to the 3 UTRs of ING5, thereby promoting cell growth and invasion in breast cancer." (PMID 40142329, 2025). "In gastric, colorectal and breast cancers, nuclear ING5 expression was negatively associated with depth of invasion, tumor size, dedifferentiation, and TNM staging, opposite to the finding of cytoplasmic ING5 expression." (PMID 36425530, 2022). "In addition, the overexpression of ING5 leads to decreased glucose metabolism, fat accumulation, autophagy and apoptosis in breast cancer cells." (PMID 33469513, 2020). "In addition, ING5 has been reported as a potential target for breast cancer and gastric cancer treatment." (PMID 31844418, 2019). "We revealed that miR-24 had the opposite effects to those of ING5 on breast cancer cells and could accelerate xenografted tumor growth in vivo." (PMID 28490335, 2017). "Taken together, these results suggest that ING5 plays an anti-tumor role in breast cancer cells." (PMID 28490335, 2017). "Indeed, downregulation of ING5 is involved in the pathogenesis of breast cancer and some other types of cancer." (PMID 28490335, 2017). "Following this theory, it is quite possible that ING5 may also affect breast cancer cell response to chemotherapeutic drugs." (PMID 28490335, 2017). "ING5 expression was higher in breast cancer than normal tissue at both mRNA and protein levels." (PMID 29137236, 2017). "In this study, ING5 is downregulated in breast cancer and is negatively regulated by miR-24." (PMID 28490335, 2017).
breast carcinoma (continued). "Finally, bioinformatics analysis showed that ING5 mRNA expression was positively linked to the favorable prognosis of the cancer patients with relapse or distant metastasis free, indicating that it might be employed as a molecular marker for a good prognosis of breast cancer." (PMID 29137236, 2017). "Our findings uncover the tumor-suppressive role of ING5 and the regulatory pathway of ING5 in breast cancer and may provide insights into the molecular mechanisms of breast carcinogenesis." (PMID 28490335, 2017). "Furthermore, we explored the molecular mechanisms accounting for the dysregulation of ING5 in breast cancer cells and identified an oncomiR, miR-24, as a direct upstream regulator of ING5." (PMID 28490335, 2017). "As potent post-transcriptional regulators of gene expression, miRNAs may be therefore involved in ING5 regulation and may well explain the disparity between ING5 protein and ING5 mRNA expression in breast cancer tissues." (PMID 28490335, 2017). "To elucidate whether miR-24 could be a regulator of ING5 protein expression in breast cancer, we determined ING5 expression levels after the overexpression or the knockdown of miR-24 in human breast cancer MCF-7 and MDA-MB-231 cells." (PMID 28490335, 2017). "Its overexpression resulted in the apoptotic induction of ING5 in breast cancer cells." (PMID 29137236, 2017). "ING5 protein level was higher in breast cancer than normal tissue by Western blot (p < 0.05)." (PMID 29137236, 2017). "Interestingly, ING4 and ING5 are also required for proliferation of breast cancer cells, supporting the hypothesis that ING proteins play pleiotropic functions in eukaryotic cells." (PMID 33925563, 2021). "Likewise, our functional study also supports the anti-tumor role of ING5 in breast cancer cells." (PMID 28490335, 2017). "The expression of nuclear ING5 was inversely linked to the aggressiveness of breast cancer, which might result from the ability of ING5 to suppress the proliferation, energy metabolism, migration, invasion and tumor growth, and induce apoptosis, and autophagy, senescent of breast cancer cells." (PMID 29137236, 2017). "Here, we found that ING5 overexpression resulted in a lower proliferation, reduced glucose metabolism, S arrest, decreased migration and invasion, apoptotic induction, fat accumulation, autophagy, senescence and mesenchymal-epithelial–transition of breast cancer cells." (PMID 29137236, 2017). "Furthermore, we provided evidence that induction of miR-24 expression could mimic ING5 suppression, stimulating the proliferation and invasion of breast cancer cells, and suppressing apoptosis." (PMID 28490335, 2017). "Taken together, the inhibitory effects of ING5 on aggressive phenotypes of breast cancer cell might account for the positive correlation between ING5 hypoexpression and aggressive behaviors or unfavorable prognosis of breast cancers." (PMID 29137236, 2017). "Further research on miR-24 and ING5 may reveal a new avenue for treatment of breast cancer." (PMID 28490335, 2017). "Although there is no related report of ING3 in breast cancer at this stage, ING4 and ING5, as members of the ING family, participate in the occurrence of breast cancer." (PMID 33469513, 2020). "Compared with the control or mock, ING5 overexpression decreased cell viability and increased chemoresistance to cisplatin, MG132, paclitaxel and SAHA in both breast cancer cells." (PMID 29137236, 2017). "To investigate the potential function of ING5 in breast tumorigenesis, we silenced ING5 expression in the MCF-7 breast cancer cell line by transfecting the cells with siRNA directed against ING5." (PMID 28490335, 2017). "Thus, induction of ING5 expression may become an attractive therapeutic strategy for breast cancer." (PMID 28490335, 2017). "We showed that the ING5 protein rather than the mRNA, was significantly downregulated in breast cancer tissues." (PMID 28490335, 2017).
breast carcinoma (continued). "First, we measured the expression levels of ING5 protein and mRNA in 8 paired human breast cancer and noncancerous tissues." (PMID 28490335, 2017). "According to Kaplan-Meier plotter, ING5 mRNA expression was not correlated with overall survival rate of the patients with breast cancer (p > 0.05), but positively with relapse- and distant metastasis-free survival rates (p < 0.05)." (PMID 29137236, 2017). "We predicted that 6 genes including ANXA1 would be regulated by miR196a using 4 prediction softwares (TargetScan, MiRanda, Diana MicroT and PicTar), and confirmed the reduction of these genes (ANXA1, HOXA7, HOXB7, ING5, CDC73 and SMURF1) by miR-196a in breast cancer cells using qPCR analysis." (PMID 27105503, 2016). "However, inconsistent alterations of the ING5 mRNA level were observed in breast cancer tissues when compared with the matched noncancerous tissues." (PMID 28490335, 2017).